MCL1 (MCL1 apoptosis regulator, BCL2 family member)
Diseases named in the same sentence as MCL1 in open-access papers (continued):
Sharing a sentence is not in itself a finding about the gene and the disease.
tumor (continued). "MCL1 is a member of the BCL2 family and its high expression is closely associated with drug resistance in tumor." (PMID 37900961, 2023). "In order to determine the association between the anti-tumor effects observed in vivo and the inhibition of MNK1 downstream signaling, XIAP and MCL1 levels were analyzed from tumor samples by western blotting." (PMID 37111758, 2023). "We demonstrate that heightened BCL-2 family protein phosphorylation modulated the apoptotic protein interactome and altered tumor cell survival dependence from BCL-2 to MCL-1, thus diminishing the sensitivity of malignant lymphoid cells to venetoclax." (PMID 37751299, 2023). "Here we show that administration of ABBV-467 to MCL-1-dependent tumor cell lines triggers rapid and mechanism-based apoptosis." (PMID 37880389, 2023). "Inhibition of SK2/DES1 by opaganib has been shown to block Akt signaling, and downregulate the expression of the c-Myc and Mcl-1 proteins, resulting in inhibition of proliferation and promotion of tumor cell death." (PMID 38069222, 2023). "While the BCL-2 inhibitor navitoclax successfully reduced metastases in mice with tumors, the MCL-1 inhibitor S63845 completely eradicated both senescent tumor cells and metastases." (PMID 37601693, 2023). "Down-regulating the expression and function of MCL-1 in tumor cells can effectively promote the apoptosis of tumor cells." (PMID 37538176, 2023). "MCL-1 is a prosurvival B-cell lymphoma 2 family protein that plays a critical role in tumor maintenance and survival and can act as a resistance factor to multiple anticancer therapies." (PMID 37880389, 2023). "A major challenge for dual BCL-xL/MCL-1 inhibition is how to safely dose and maintain tumor efficacy in the mouse and, more importantly, in the patient setting." (PMID 37210412, 2023). "Recently, it has been described that treatment with the Mcl-1 inhibitor S63845 leads to the complete elimination of senescent tumor cells and metastases." (PMID 37047342, 2023). "Consistent with our in vitro results, we observed reduced levels of LC3B, pEGFR, pAKT and MCL1 in tumor tissue from AMG9810-treated mice compared to vehicle-treated mice." (PMID 37165076, 2023). "As Bcl-xL, Mcl-1 acts as a senescence inhibitor, since the overexpression of Mcl-1 in tumor cells is crucial for blocking the induction of senescence." (PMID 37047342, 2023). "Targeting myeloid cell leukemia-1 (MCL-1) protein is a successful strategy to induce apoptosis and overcome tumor resistance to chemotherapy and targeted therapy." (PMID 37601693, 2023). "NA1-115-7 is the latest type of selective Mcl-1 inhibitor that specifically induces apoptosis in Mcl-1-dependent tumor cells, and two hours of treatment is sufficient to trigger cell death." (PMID 37259388, 2023). "This was achieved by selective degradation of BCL-XL and inhibition of MCL-1 expression in tumor cells with DT2216 and AZD8055, respectively, therefore reducing on-target toxicity to platelets and other normal cells." (PMID 36588105, 2023). "In sharp contrast, the MCL1 inhibitor S63845 induced more tumour cell killing in the CDDP cells compared to the parental spheroids." (PMID 37723317, 2023). "GSK-3β has important roles as both a tumor suppressor (e.g., inhibition of β-catenin, c-Myc, and Mcl-1) and promoter (e.g., inhibition of the cell cycle inhibitor p27Kip1)." (PMID 36674871, 2023). "Combined AFP immunization and anti-PD1 treatment significantly suppress c-MYC/Mcl1 tumor progression." (PMID 37040183, 2023). "While Navitoclax minimizes the occurrence of metastasis in vivo, S63845, a Mcl-1 inhibitor, completely eradicates both senescent tumor cells and metastasis." (PMID 36980256, 2023). "Data analysis revealed that bergenin downregulated Mcl-1 expression in tumor tissues and significantly decreased the population of Ki67-positive cells." (PMID 37259388, 2023). "Mcl-1, another member of the Bcl-2 family, similarly exhibits cell survival influences on tumor growth through overexpression." (PMID 37686541, 2023).
tumor (continued). "The histological evaluation revealed that LPs were able to co-deliver GEM and Mcl-1-siRNA at the same tumour site, hence overcoming GEM resistance and preventing siRNA serum degradation." (PMID 36635659, 2023). "In summary, the molecule ABBV-467 is a highly potent and selective MCL-1 inhibitor that demonstrates robust inhibition of tumor growth in in vivo models of hematological malignancies." (PMID 37880389, 2023). "USP9x-mediated stabilization of Mcl-1 protein levels by preventing its degradation was described before as a mechanism that increased apoptosis threshold in other tumor entities." (PMID 37173959, 2023). "The use of combined MCL1 inhibitors with cisplatin in TNBC effectively initiates TAp73 anti-tumor effects on cell cycle arrest and apoptosis." (PMID 37760451, 2023). "We further tested canonical apoptosis inducers BH3-mimetics such as navitoclax and venetoclax (BCL-2 inhibitors), as well as S63845 (MCL-1 inhibitor) and found both robust nuclear bursting and calcium spike in 4T1 tumor cells." (PMID 36973439, 2023). "In a direct comparison of cisplatin-resistant cells we identified a prominent loss of sensitivity to BCL2/BCL-XL inhibitors that is associated with an increase in MCL1 dependency and high expression of MCL1 in patient tumour tissues." (PMID 37723317, 2023). "Translationally Controlled Tumor Protein (TCTP) serves as a pro-survival factor in tumor cells, inhibiting the mitochondrial apoptosis pathway by enhancing the function of anti-apoptotic Bcl-2 family members Mcl-1 and Bcl-xL." (PMID 37201583, 2023). "Next, we confirmed that DT2216 and AZD8055 led to a significant reduction in BCL-XL and MCL-1 levels, respectively, which was associated with significant inhibition of mTOR substrates (p-4EBP1 and p-S6) upon AZD8055 treatment in H1048 tumor lysates." (PMID 36588105, 2023). "In summary, the findings indicate that combined anti–PD-L1 and AFP immunization increased activated CD8+ T cells, including AFP499+ CTLs, inducing the dramatic inhibition of most tumor lesions in c-MYC/Mcl1 mice." (PMID 37040183, 2023). "Unfortunately, the single-agent efficacy of navitoclax against SCLC in phase-II clinical trials was limited because of the intratumoral heterogeneity and dependence of some of the cells within a tumor on other BCL-2 family proteins such as MCL-1." (PMID 36588105, 2023). "S63845 binds human MCL-1 with 6-fold higher affinity than murine MCL-1, yet was still able to reduce tumor burden in mice." (PMID 37864894, 2023). "FBXW7 acts as a tumor suppressor by promoting the ubiquitination and degradation of various substrates including c-Myc, c-Jun, cyclin E, and MCL-1, which usually function as oncoproteins and promote tumor growth and survival." (PMID 37006236, 2023). "Western blotting results confirmed that vortioxetine hydrobromide reduced the levels of p-STAT3 Y705, c-Myc, Bcl-2 and Mcl-1 in PDX tumor xenografts." (PMID 37147297, 2023). "More importantly, BCL-XL/MCL-1 co-dependent tumor cells cannot be safely targeted with the currently available inhibitors because the combination of BCL-XL and MCL-1 inhibitors causes severe tissue damage and lethality in mice." (PMID 36588105, 2023). "Mcl-1 is an antiapoptotic protein of the Bcl-2 family that has been listed as a common target of cardiac glycoside UNBS1450 in a panel of tumor cells of different origins, e.g., lung, prostate, breast, blood and nerve tissue." (PMID 37828578, 2023). "Myeloid cell leukaemia sequence 1 (Mcl-1), an anti-apoptotic Bcl-2 family member, is overexpressed in many tumour types, including HCC." (PMID 37663116, 2023). "Pharmacologic targeting of CDK9 has shown promising in vitro and in vivo anti-tumor activity in malignancies that exhibit dependence on Mcl-1 and/or MYC." (PMID 36998071, 2023). "The inhibition of MCL-1 was able to increase the sensitivity of tumor cells to venetoclax (in vitro) and induced tumor regression in vivo with the same agent." (PMID 37720343, 2023).
tumor (continued). "Although few studies have addressed this concern so far, it is plausible that a similar mechanism would occur for MCL-1 when treating tumor cells with a BH3-mimetic MCL-1 inhibitor." (PMID 37684238, 2023). "In tumor cells isolated from patients on the trial, we noted a significant decrease in Bcl-2:Bim or Mcl-1:Noxa complexes after 1 full cycle of treatment, suggesting increased availability of Bim to trigger mitochondrial-mediated programmed cell death." (PMID 36672426, 2023). "Previous studies have demonstrated that the high expression of MCL-1 is an important reason for the insensitivity of tumor cells to venetoclax." (PMID 37352173, 2023). "In del[13q]CLL cells, the microRNA (miR) cluster miR-15a/miR-16-1 is deleted, leading to the loss of its tumor suppression function and overexpression of the antiapoptotic proteins B-cell lymphoma-2 (BCL-2) and myeloid cell leukemia-1 (MCL-1)." (PMID 37228498, 2023). "PROTAC, therefore, offers a great potential to induce tumor cell death by specifically triggering Mcl-1 degradation and efforts are underway to develop PROTAC probes for Mcl-1 with high sensitivity." (PMID 36045907, 2022). "The unique structure of Mcl-1 and its complex regulatory mechanism makes it an adaptive prosurvival switch that ensures tumor cell survival despite therapeutic intervention." (PMID 36045907, 2022). "Deubiquitinases USP9X, Ku70, JOSD1, DUB3/USP17L2, and USP13 have been described to stabilize Mcl-1, promote tumor cell survival and suppress apoptosis." (PMID 35301297, 2022). "Since Bcl-2 expression is limited in CRC tumor samples, we subsequently sought to understand the impact of nuclear MCL1 on the activity of the Bcl-xL inhibitor A-1331852." (PMID 35042842, 2022). "Mcl-1 is upregulated in senescent tumor cells, including cells expressing low levels of Bcl-2, an established target for senolytic therapy." (PMID 35449130, 2022). "All cell lines displayed increased PI uptake by combined treatment with A1331852 and S63845, confirming that simultaneous inhibition of Mcl-1 and Bcl-XL induced cell death in tumor spheroids." (PMID 35013156, 2022). "Tumor-bearing S26-R cells with MCL-1 depletion grew slowly compared with S26-R cells with control shRNA treatment." (PMID 35136016, 2022). "Activation of antiapoptotic Bcl-2 family proteins, such as Bcl-2, Mcl-1, and Bcl-xL, are frequently observed in chemoresistant tumor cells, offsetting the functions of proapoptotic Bcl-2 family proteins and suppressing apoptosis." (PMID 36430955, 2022). "More interestingly, radotinib inhibited the STAT3-targeted proteins such as Bcl-xl, Mcl-1, c-Myc, and cyclin D3 expression in IM-9 cells isolated from the tumor tissue." (PMID 35503759, 2022). "There remains uncertainty concerning the true proportion of PBs with MCL1 amplification, although our cohort comprising 13 analyzable patient samples can be regarded as one of the larger series for this very rare tumor." (PMID 35668118, 2022). "In particular, MALAT1 is able to sponge the tumor suppressor miRNA miR-363-3p, derepressing the MCL1 apoptosis regulator (MCL1) oncogene, a target of miR-363-3p." (PMID 35804851, 2022). "Combining BH3 mimetics has also emerged as a promising strategy to target BCL-2 protein-mediated resistance and enhance tumour cell killing, with early in vitro studies showing that MCL-1 knockdown overcomes ABT-737 resistance." (PMID 35568716, 2022). "Of note, inactivation of Mcl-1 in cells treated with TIS efficiently eliminated senescent tumor cells." (PMID 35449130, 2022). "Studies had shown that tumor cells with high expression of anti-apoptotic protein MCL-1 have primary resistance to the BCL-2 selective inhibitor." (PMID 35794605, 2022).
tumor (continued). "Since Mcl-1 protein is critical for survival, tumor cells maintain its sustained elevated levels partly through its posttranslational stabilization-deubiquitination." (PMID 36045907, 2022). "It has been well characterized in several tumor entities, and MCL1 inhibitors have shown efficacy in preclinical trials for hematological neoplasms and solid tumors." (PMID 35668118, 2022). "As a recent report has shown that MCL1 can regulate AKT phosphorylation in tumour cells, we first confirmed the downregulation of MCL1 expression in the IDs KO lines by WB and qPCR analyses." (PMID 35701409, 2022). "The upregulation of Noxa acts as a link between the osmotic pressure in the tumor environment and mitochondrial priming, thereby counteracting the anti-apoptotic properties of Mcl-1 in head and neck SCC." (PMID 35524332, 2022). "Our data are the first to highlight a role for the loop domain of MCL1 to be important for tumor cell-survival and resistance to chemotherapy." (PMID 35042842, 2022). "Percentages of tumor cells with ≥ 4.0 gene copies were 2% and 20%, respectively, but MCL1/1p12 ratio was < 2.0 and average gene copy number was < 3.0 in both samples." (PMID 35668118, 2022). "Here, using single-cell RNA-sequencing, we find that senescent tumor cells rely on the anti-apoptotic gene Mcl-1 for their survival." (PMID 35449130, 2022). "This review focusses on diverse mechanisms adopted by tumor cells to maintain sustained elevated levels of Mcl-1 and how high Mcl-1 levels contribute to resistance in conventional as well as targeted therapies." (PMID 36045907, 2022). "Collectively these data imply that tumor resistance to doxorubicin mediated by MCL1 nuclear translocation can be overcome by treatment with small molecule inhibitors of Bcl-xL, A-1331852, but this mechanism is dependent upon ENO1." (PMID 35042842, 2022). "We observed a substantial impairment of tumour growth in MCL-1 deleted tumours that was reflected in the significantly prolonged survival of these mice." (PMID 35473984, 2022). "FBXW7 promotes ubiquitination and degradation of myeloid leukemia 1 (MCL-1) a member of the pro-survival Bcl-2 family regulating apoptosis in tumor cells." (PMID 35346215, 2022). "In fact several genes such as CKS1B, PSMD4, IL6R, MCL1 involved in proliferation and survival of tumour cells, mechanisms of chemo refractoriness, and alteration of the microenvironment are located in the 1q21 region." (PMID 36755858, 2022). "In all cases, we found that a combined therapy with A-1331852 and S63845 (BCL-xL and MCL-1 inhibition) significantly reduced tumour cell count compared with single drug treatment or control." (PMID 35473984, 2022). "The ability of MCL1 to inhibit the induction of apoptosis is well defined, facilitating tumor initiation and maintenance and driving chemoresistance." (PMID 35042842, 2022). "The weakening of apoptosis often leads to tumorigenesis, and the overexpression of antiapoptotic oncogenes such as BCL-2/BCL-XL, MCL1 or the IAP proteins is conducive to the survival of tumor cells." (PMID 36713522, 2022). "After reviewing the literature, we found that MCL1 was a key protein related to cell cycle and that MCL1 was significantly overexpressed in tumor tissues with radiotherapy resistance." (PMID 36262872, 2022). "Many tumour cells over-express Mcl-1 protein, resulting in the imbalance of interaction between anti-apoptotic members and pro-apoptotic members, leading to malignant proliferation of tumour cells." (PMID 36386146, 2022). "Via sponging miR-193a-3p, circHIPK3 promoted myeloid cell leukemia 1 (MCL1) expression, and activated PCa cell growth and tumor progression." (PMID 36292157, 2022). "While treatment with the Bcl-2 inhibitor Navitoclax results in the reduction of metastases in tumor bearing mice, treatment with the Mcl-1 inhibitor S63845 leads to complete elimination of senescent tumor cells and metastases." (PMID 35449130, 2022).
tumor (continued). "Many evidences have expounded that MCL1 also participates in tumor development and is under the mediation of miRNA." (PMID 35266447, 2022). "Combination treatment suppressed tumor growth to a greater extent than either agent alone, indicating the requirement of both Mcl-1 and Bcl-2/Bcl-xL inhibition for effective ER+ tumor suppression." (PMID 35053443, 2022). "AITC significantly downregulated the protein expression levels of MCL-1, XIAP, MMP-9, and VEGF; however, it increased apoptosis-associated proteins, such as cleaved caspase-3, -8, and -9, in the tumor tissues compared with the control group." (PMID 36142326, 2022). "Downregulation of Mcl-1 upon mTOR inhibition was accompanied by a reduction in tumor volume, which was further reduced upon co-treatment with the Bcl-2/Bcl-xL inhibitor ABT-263." (PMID 35053443, 2022). "Bax/Bak-deficient tumors were shown to be resistant to Mcl-1 inhibition, whereas the presence of Bax/Bak in MCL1-deficient mice resulted in long-term tumor suppression." (PMID 35053443, 2022). "Targeted downregulation or pharmacological inhibition of Mcl-1 in combination with the BRAF inhibitors increased the tumor cell killing efficacy." (PMID 36045907, 2022). "For example, IL-6 interacts with the receptor JAK and induces STAT-3 activation, which triggers oncogenes such as myeloid cell leukemia-1 (MCL-1) and upregulates proliferative genes, Cyclin-D1, in tumor cells." (PMID 36613591, 2022). "To identify the underlying mechanism of tumor growth inhibition, we further investigated the alteration of tumor-progression-related protein expression, including MCL-1, XIAP, MMP-9, and VEGF after AITC treatment by IHC staining of tumor tissues." (PMID 36142326, 2022). "A novel small‐molecule BI‐44 was synthesized, which suppressed BMI1/MCL1 expression and showed significant anti‐tumour effect in preclinical models, providing a new and promising approach for NSCLC treatment." (PMID 35794816, 2022). "In the present study, we chose ApoG2, the most potent derivative of gossypol with high affinity against anti-apoptotic Bcl-2 family members (pan-Bcl-2 inhibitor), including Bcl-2, Bcl-XL and Mcl-1 in tumor-targeted treatment." (PMID 35924156, 2022). "The regulation of cofilin phosphorylation by Myeloid cell leukemia 1 (MCL-1) is associated with tumor cell activity in B-cell lymphoma 2, and the inhibition of this effect of MCL-1 has become important for tumor therapy." (PMID 35371070, 2022). "The dramatic effect of perturbing Mcl-1 dependence on tumor development underscores the need for tumor cells to maintain Mcl-1 expression and stability." (PMID 35457012, 2022). "The novel small‐molecule BI‐44 developed in this study effectively suppressed BMI1/MCL1 expressions and inhibited tumour initiation and progression in preclinical models." (PMID 35794816, 2022). "Noxa is a BH3-only pro-apoptotic protein that inactivates the anti-apoptotic molecule Mcl1 and thus plays a key role in inducing tumor cell death by cisplatin." (PMID 35897737, 2022). "Even though MCL1 amplifications are low in CRC cell lines compared to other human tumor cell lines, MCL1 can still limit the activity of Bcl-xL inhibitors and other chemotherapeutic agents in CRC and additional solid tumor indications." (PMID 35042842, 2022). "H19 sustains tumor growth and bortezomib resistance by inhibiting the tumor suppressor miR-29b-3p and by increasing the levels of the anti-apoptotic protein MCL-1." (PMID 35454868, 2022). "Mcl-1 is frequently overexpressed in human tumors and contributes to tumor development, progression, and poor prognosis." (PMID 35301297, 2022). "In OS, MCL-1 expression is upregulated after chemotherapy, and high MCL-1 expression is associated with poor overall survival, increased recurrence rate, decreased sensitivity to MTX, and promotion of tumor proliferation." (PMID 36176756, 2022).